APOM (apolipoprotein M)
Diseases named in the same sentence as APOM in open-access papers (continued):
Sharing a sentence is not in itself a finding about the gene and the disease.
coronary artery disease (13 papers, 2013 to 2025). "The apolipoprotein M (APOM) T-778C gene polymorphism has been associated with serum lipid levels and the risk of coronary artery disease (CAD), but the results are inconclusive." (PMID 24040766, 2013). "Others have reported that single nucleotide polymorphisms with a reduction in ApoM transcriptional activity and a decrease in serum ApoM levels may be biomarkers for coronary artery disease." (PMID 36980195, 2023). "Clinically, blood plasma or serum concentrations of both S1P and ApoM have been linked to human diseases such as sepsis, coronary artery disease (CAD), type I and II diabetes (T1/IID), systemic lupus erythematosus (SLE), and most recently, COVID." (PMID 40386785, 2025). "A single nucleotide polymorphism with a reduction in ApoM transcriptional activity and a decrease in serum ApoM levels has been reported as a potential biomarker for coronary artery disease." (PMID 36980195, 2023). "It has been reported that rs940494 and rs805296 SNPs of apolipoprotein M (apoM) gene may confer the risk in the development of type 2 diabetes (T2D) and coronary artery disease (CAD) in the Han Chinese." (PMID 24341666, 2013). "Factors associated with apoM, COPD, or coronary artery disease (CAD) were also assessed." (PMID 27001252, 2016). "In asymptomatic familial hypercholesterolemia patients, higher macrophage cholesterol efflux capacity, as well as higher S1P and apoM content of HDL, were found, suggesting a potential protective role against premature coronary heart disease." (PMID 34064071, 2021). "ApoM levels were reported as a potential biomarker for coronary artery disease; however, another study did not identify apoM as a predictor of coronary heart events." (PMID 34064071, 2021). "In two independent case–control studies, the mean HDL-C level is significantly lower in coronary heart disease patients than in control subjects, but the mean apoM levels do not significantly differ between the two groups." (PMID 27633510, 2016).
hepatoma (10 papers, 2008 to 2023). "As for OGs, for the 21 best ranked TSGs, we found many publications indicating their role in cancer, and strikingly, APOM is actually a known TSG for hepatocellular carcinoma." (PMID 31568528, 2019). "RES has been found to exert a biphasic effect on apolipoprotein M (apoM) in hepatoma cells and C57BL/6 mice." (PMID 31159437, 2019). "Finally, functional assays suggest that BFL-1 plays a role in the resistance of hepatoma cells to apoptosis induced by apolipoprotein M, a liver lipoprotein which can supress migration, invasion, and proliferation of hepatoma cells." (PMID 35900226, 2022). "In the mouse, leptin the “satiety” hormone and leptin receptor are essential for expression of ApoM, but excess concentrations of leptin inhibited ApoM mRNA expression in a dose-dependent manner in the human hepatoma cell line HepG2, suggesting that leptin may mediate ApoM expression." (PMID 35945490, 2022). "However, ApoM over-expression promotes apoptosis in the human hepatoma derived cell line HepG2." (PMID 28179022, 2017). "Moreover, addition of TNF or IL-1 to Hep3B hepatoma cell cultures decreases apoM mRNA levels." (PMID 22512779, 2012). "Apolipoprotein M (APOM) can suppress the proliferation and invasion of hepatocellular carcinoma, breast cancer, and larynx carcinoma." (PMID 37848935, 2023). "Treatment of HepG2 hepatoma cells with SR-BI specific inhibitor, BLT-1, could up-regulate ApoM expression in serum-containing medium but not in serum-free medium, even in the presence of HDL-C and cholesterol." (PMID 30144814, 2018).
Hyperglycemia (9 papers, 2004 to 2026). An increased concentration of glucose in the blood. "Hyperglycaemia can stimulate the hexosamine pathway and cause an increase in endogenous glucosamine levels, but both exogenous and endogenous glucosamines can increase the apoM expression in HepG2 cells and in rat models." (PMID 27633510, 2016). "In the context of DN, hyperglycemia disrupts this reciprocal relationship, leading to a detrimental cycle of impaired mitophagy and reduced ApoM, which exacerbates renal injury." (PMID 41858086, 2026). "In the present we investigated if glucosamine, a common subject of hexosamine biosynthesis pathway,being responsible for hyperglycemia-induced suppression of apoM expression." (PMID 26377577, 2015). "In the present study we further examined if hexosamine pathway, one of the most important pathways of glucose turnover, being involved in modulating apoM expression in the hyperglycemia condition." (PMID 26377577, 2015). "We hypothesized that hyperglycemia induced down-regulation of apoM expression may mediate via the glucosamine pathway." (PMID 26377577, 2015). "We previously demonstrated that hyperglycemia could suppress apolipoprotein M (apoM) synthesis both in vivo and in vitro; however, the mechanism of hyperglycemia-induced downregulation of apoM expression is unknown yet." (PMID 26377577, 2015). "We previously reported that hyperglycemia could significantly down-regulate apoM expression either in vivo or in vitro, which could be reversed by rosiglitazone in vivo, but it’s mechanism is unknown yet." (PMID 26377577, 2015). "Hyperglycemia was shown to down-regulate the expression of apoM in vivo and in vitro, but the mechanism was still unknown." (PMID 26377577, 2015). "Futhermore, Serum apoM concentrations and hepatic APOM mRNA levels were significantly reduced in the hyperglycemic rats, indicating that the low expression levels of apoM in these diabetic animals could be ascribed to hyperglycemia." (PMID 24642298, 2014). "Animals and cell culture suggested that hyperglycemia could down-regulate apoM expression." (PMID 27576735, 2016). "Serum apoM concentrations and hepatic apoM mRNA levels were significantly reduced in the hyperglycemic rats, indicating that the low expression levels of apoM in these diabetic animals could be ascribed to hyperglycemia." (PMID 24642298, 2014). "Serum levels of apoM were significantly decreased in HNF-1α /MODY3 subjects when compared with control subjects as well as with HNF-4α /MODY1 subjects, indicating that HNF-1α haploinsufficiency rather than hyperglycemia is the primary cause of decreased serum apoM protein concentrations." (PMID 15461812, 2004). "Hyperglycemia induced down-regulation of apolipoprotein M expression is not via the hexosamine pathway." (PMID 26377577, 2015). "It is concluded that both exogenous and endogenous glucosamine were essential for the over-expression of apoM, which may suggest that the increased intracellular content of glucosamine does not be responsible for the depressed apoM expression at hyperglycemia condition." (PMID 26377577, 2015).
type 1 diabetes (9 papers, 2016 to 2025). "Of the remaining five genes, three [MICA, NCR3, and TAP2] have been previously associated with type 1 diabetes, while APOM and HLA-DRB5 have been associated with RA." (PMID 32245788, 2020). "Certain SNPs of ApoM have been associated with type 1 diabetes." (PMID 40019499, 2025). "Although patients with type 1 diabetes have normal plasma apoM levels, the apoM/S1P complex shifts from small, dense HDL to larger, less dense HDL particles." (PMID 33260660, 2020). "In addition, streptozotocin-induced type 1 diabetes resulted in increased apoM levels, which were reversed by insulin treatment, while age induced a decrease in apoM levels in mice." (PMID 34722589, 2021). "The association of the apoM/S1P complex with larger, less dense HDL particles attenuates the anti-inflammatory effects of HDL, which could lead to elevated cardiovascular disease risk associated with type 1 diabetes." (PMID 33260660, 2020). "In humans with type 1 diabetes, the ApoM-S1P complex shifts to larger HDLs that provide less protective endothelial function compared with dense HDL-ApoM-S1P from controls." (PMID 35362476, 2022).
chronic kidney disease (7 papers, 2021 to 2026). Impairment of the renal function secondary to chronic kidney damage persisting for three or more months. "In contrast, apoM levels in patients with CKD of mixed etiology are negatively associated with CKD severity, while plasma apoM levels in patients with end-stage renal disease are lower than those in controls." (PMID 34722589, 2021). "A study conducted in patients with chronic kidney disease (CKD), of whom 30% also suffered from T2D, showed a reduction in plasma apoM levels with severity of CKD in a cohort of more than 400 patients and 35 controls." (PMID 34093440, 2021). "In humans, patients with stage 3 or higher chronic kidney disease (CKD) and cardiovascular disease have lower ApoM levels than those with stage 1 and 2 CKD without cardiovascular disease." (PMID 40579063, 2025).
endothelial dysfunction (7 papers, 2019 to 2025). In vascular diseases, endothelial dysfunction is a systemic pathological state of the endothelium (the inner lining of blood vessels) and can be broadly defined as an imbalance between vasodilating and vasoconstricting substances produced by (or acting on) the endothelium. "A limitation of our study is the lack of mechanistic evidence for any causality of our finding that low apoM levels are associated with endothelial dysfunction in SLE specifically." (PMID 31046824, 2019). "An increase in urate levels may be a risk factor for endothelial dysfunction, a process that, particularly in older individuals who are more vulnerable to chronic inflammation, can lead to downregulation of ApoM expression." (PMID 40758327, 2025). "ApoM modulates endothelial dysfunction primarily through its role as a carrier of S1P on high-density lipoprotein (HDL) particles." (PMID 41303567, 2025). "Another apolipoprotein, APOM, is overexpressed before PE onset, contributing to defective placentation and endothelial dysfunction through its roles in inflammation, lipid transport, and metabolism." (PMID 39408980, 2024). "We hypothesize that SLE-related inflammation may lead to lower plasma apoM levels that might contribute to endothelial dysfunction." (PMID 31046824, 2019). "Given their possible involvement in key molecular pathways—ranging from oxidative stress and low-grade inflammation to endothelial dysfunction, altered mineral metabolism and tissue remodeling—RBP4, LCN2, ApoM, Klotho and MGP represent more than isolated biomarkers." (PMID 41303567, 2025). "Since apoM represents the main carrier of the vasoprotective S1P, the reduction of apoM on GDM HDL might contribute to endothelial dysfunction observed in GDM." (PMID 33808220, 2021). "ApoM levels may be regulated by SLE-related inflammatory processes and could be a marker of disease activity and endothelial dysfunction, in particular in young SLE patients." (PMID 31046824, 2019).
Hyperinsulinemia (7 papers, 2014 to 2024). An increased concentration of insulin in the blood. "In such studies, it would be important to remember that hyperinsulinemia exerts opposing effects on plasma apoM and S1P levels, which adds to the complexity of their relationship." (PMID 34093440, 2021). "In subsequent studies, the potential bias introduced by the hyperinsulinemia-induced reduction in plasma apoM and increase in plasma S1P levels should be considered carefully." (PMID 34093440, 2021). "In this review, the consumption of an HFD can increase the S1P levels, whereas in apoM-expressing models, HFD reduce apoM levels via the negative regulation of hyperinsulinemia." (PMID 34093440, 2021).
Hypertension (7 papers, 2013 to 2026). The presence of chronic increased pressure in the systemic arterial system. "S1P‐binding ApoM‐Fc reduces hypertension while increased hematopoietic SphKs activity promotes hypertension." (PMID 32803879, 2020). "First, we compared genotype distributions and allele frequencies of the apoM gene between CAD and control groups and then performed a logistic regression with adjustments for age, sex, BMI, history of smoking, hypertension and hypercholesterolemia." (PMID 24341666, 2013). "Additionally, apoM levels were lower in subjects with hypertension, in accordance with its role in reducing blood pressure in hypertensive mice." (PMID 38491190, 2024).
colorectal cancer (6 papers, 2010 to 2022). A primary or metastatic malignant neoplasm that affects the colon or rectum. "In contrast, colorectal cancer patients with lymphatic metastasis express significantly higher levels of apoM mRNA in colorectal tissues." (PMID 32306242, 2020). "ApoM has been demonstrated to be involved in the development of different types of tumor, such as colorectal cancer and lung carcinoma." (PMID 32306242, 2020). "For example, in 2010, we found that colorectal cancer patients with lymph node metastasis expressed significantly high levels of APOM mRNA10." (PMID 33173129, 2020). "In the present study, we demonstrated that apoM was abundantly expressed in normal colorectal tissues and with inhibited levels found in the colorectal cancer tissues." (PMID 20846402, 2010). "In parallel, apoM mRNA levels in the colorectal cancer tissues (0.0536 ± 0.0131) were also significantly lower than those in their adjacent normal tissues (0.1907 ± 0.0563) (P = 0.033)." (PMID 20846402, 2010). "Perhaps apoM mRNA levels in colorectal cancer tissues can be determined for evaluating the metastasis, and further for patient's prognosis." (PMID 20846402, 2010). "ApoM mRNA levels in colorectal cancer tissues (0.0536 ± 0.0131) were significantly lower than those in their adjacent normal tissues (0.1907 ± 0.0563) (P = 0.033)." (PMID 20846402, 2010). "ApoM mRNA levels in the colorectal cancer tissues were significantly increased in the patients with lymph node metastasis." (PMID 20846402, 2010). "In the present study we investigated whether apoM presented in human colorectal tissues and further investigated the difference of apoM expression pattern in colorectal tissues from patients with colorectal cancer and benign diseases." (PMID 20846402, 2010). "Interestingly, apoM mRNA levels were significantly increased in the colorectal cancer tissues of patients with lymph node metastasis than the patients without lymph node metastasis." (PMID 20846402, 2010). "Interestingly, apoM mRNA levels in colorectal cancer tissues were statistic significant higher in the patients with lymph node metastasis than the patients without lymph node metastasis (P = 0.008)." (PMID 20846402, 2010). "This may suggest, although apoM expression is obviously decreased in the colorectal cancer tissues than in normal tissues, there are certain factors or mechanism could up-regulate apoM expression during the progress of the cancers." (PMID 20846402, 2010). "However, apoM protein mass in the colorectal cancer tissues were significantly decreased compared to its adjacent tissues." (PMID 20846402, 2010). "Moreover we demonstrated that apoM mRNA levels were significantly increased in the colorectal cancer tissues of patients with lymph node metastasis, although apoM expression in cancer tissues was generally much lower than in normal colorectal tissues." (PMID 20846402, 2010). "Determination of apoM mRNA in the surgical resected colorectal cancer tissues may have potential benefit for evaluating patient's prognosis." (PMID 20846402, 2010). "Additionally, in 2017, we also found that APOM increased the levels of vitamin D receptor (VDR) in colorectal cancer cells, suggesting that APOM may play an antineoplastic role by upregulating the expression of VDR11." (PMID 33173129, 2020). "In colorectal cancer (CRC), a study also indicates the similar relationship between ApoM and VDR but the role of ApoM in the cancer remains controversial." (PMID 36506554, 2022). "Neither apoM mRNA levels nor apoM protein concentrations in the colorectal cancer tissues were correlated to patients' sex, age, tumor stage, tumor size and tumor locations." (PMID 20846402, 2010). "Under immunochemical staining, apoM protein was mainly located in normal columnar epithelial cells of the colorectal mucosa and non-regularly stained in the colorectal carcinoma cells." (PMID 20846402, 2010).
systemic lupus erythematosus (6 papers, 2017 to 2025). An autoimmune multi-organ disease typically associated with vasculopathy and autoantibody production. "In this study, we tested the hypothesis that common promoter variation in the APOM gene is associated with systemic lupus erythematosus (SLE) risk and SLE-related clinical phenotypes in a Chinese cohort." (PMID 28476116, 2017). "Plasma concentrations of apoM were measured by ELISA in two patient groups with systemic lupus erythematosus (SLE) and in 79 healthy control individuals." (PMID 31046824, 2019). "Meanwhile, we investigated the expression of apolipoprotein M (APOM) in the serum of patients with systemic lupus erythematosus (SLE) and its relationship with disease activity." (PMID 28476116, 2017). "In other inflammatory diseases, such as sepsis, psoriasis and systemic lupus erythematosus (SLE), apoM levels are also reduced, which might contribute to the disturbance of HDL composition and its function." (PMID 33260660, 2020). "Given wide-stretched linkage disequilibrium to the area APOM/BAG6/MSH5, there is currently simply not enough information or evidence to conclude whether the potential pleiotropy of lung cancer and systemic lupus erythematosus is spurious, biological, or mediated." (PMID 28273134, 2017).
Alzheimer disease (5 papers, 2015 to 2025). A progressive, neurodegenerative disease characterized by loss of function and death of nerve cells in several areas of the brain leading to loss of cognitive function such as memory and language. "ApoM is centrally involved in regulating cholesterol metabolism and turnover, while also being implicated in the onset of Alzheimer’s disease." (PMID 39827160, 2025). "In the recent genetic meta-analysis of Alzheimer’s disease, several genes were implicated in lipid processing, including APOM, APOA5, and ABCA1." (PMID 33166319, 2020). "Recent evidence of genetics and metabonomics indicated a potential role of apolipoprotein M (ApoM) in the pathogenesis of Alzheimer’s disease (AD)." (PMID 35370599, 2022). "Alzheimer’s disease group had a significantly higher plasma ApoM level [52.66 (41.20–61.44) vs. p < 0.0001] than CN group." (PMID 35370599, 2022). "Finally, we successfully verified significantly lower levels (p<0.05) of eight proteins (A2GL, APOM, C1QB, C1QC, C1S, FBLN3, PTPRZ, and SEZ6) in Alzheimer’s disease compared to controls using an antibody-based detection method." (PMID 26950848, 2016).
diabetic nephropathy (5 papers, 2021 to 2026). "The knockout of apolipoprotein M also exacerbated the progression of glomerular disease in an STZ-injected mouse model, while apolipoprotein M overexpression through adenoviral vector injection reduced diabetic nephropathy phenotypes." (PMID 38891023, 2024). "ApoM could act as a valuable biomarker for predicting the progression of diabetic nephropathy, and the ApoM/S1P–S1P1 axis might emerge as a new therapeutic target for its prevention and treatment." (PMID 39777222, 2024).
familial hypercholesterolemia (5 papers, 2013 to 2022). An inheritable form of hyperlipidemia, in which there are excess lipids in the blood. "Thus, BMI and T2D are inversely associated with apoM levels, while familial hypercholesterolemia with an isolated increase in LDL-C level is associated with an increase in plasma levels of apoM." (PMID 34722589, 2021). "Our results demonstrate the complex regulatory role of the ApoM/S1P complex on vascular function in HeFH patients and highlight the importance of further studies to clarify the consequences of high ApoM and S1P concentrations in heterozygous familial hypercholesterolemia." (PMID 36430543, 2022).